MTOR (mechanistic target of rapamycin kinase)
Diseases named in the same sentence as MTOR in open-access papers (continued):
Sharing a sentence is not in itself a finding about the gene and the disease.
cancer (continued). "PI3K-Akt-mTOR is an important signaling pathway that affects cell energy metabolism, proliferation, apoptosis, the cell cycle, cell size, and cell invasion and survival times, and is closely associated with many types of cancers." (PMID 29212166, 2017). "Alterations resulting in PTEN loss and PIK3CA amplification, which are also targets for mTOR/P13K inhibitors, have been implicated in 7% and 9% respectively, in carcinomas of unknown primary." (PMID 28302097, 2017). "To date, only 20 of 129 common SNPs within mTOR have been investigated in relation to cancer risk." (PMID 27462867, 2016). "As the mTOR pathway is a central controller of cellular growth, excessive activation caused by mutations or other changes in upstream pathways confers a growth advantage to cancer cells." (PMID 27462867, 2016). "The mammalian target of rapamycin (mTOR) is a master regulator of nutrient sensing (mTORC2) and growth factor signaling (mTORC1) in normal cells and its dysfunction is implicated in the malignant transformation for a variety of cancer types." (PMID 27765027, 2016). "Additionally, deregulation of the PI3K/Akt/mTOR signaling pathway is also associated with human cancer therapy." (PMID 27248997, 2016). "In addition, the PI3KCA/AKT/mTOR/Survivin pathway has been associated with 5FU, cisplatin and resistance to other DNA-damaging agents in many types of cancer." (PMID 27517495, 2016). "Activation of the phosphatidylinositide‐3‐kinase (PI3K)/serine/threonine‐specific protein kinase (AKT)/mammalian target of rapamycin (mTOR) pathway has been implicated in the growth and progression of various cancers, as well as resistance to standard anticancer therapies." (PMID 26715098, 2016). "This “reprogrammed” metabolic state is highly susceptible to mTOR-KI treatment and may predict therapeutic efficacy in cancer patients." (PMID 27015560, 2016). "This study also paves a new avenue to treat AIM2-deficient cancer by suppression of mTOR." (PMID 27167192, 2016). "Mutant mTOR proteins caused by point mutations around the kinase domain of mTOR demonstrate constitutive activation, and have been shown to affect cell cycle progression and cell size in human cancers." (PMID 27462867, 2016). "Aberrant mTOR signaling pathway has been implicated in the pathogenesis of many diseases including cancer and targeting mTOR signaling pathway may be a promising strategy for cancer therapy." (PMID 26840285, 2016). "Several studies assessed mTOR haplotype effects on cancer risk." (PMID 27462867, 2016). "The PI3K/AKT/mTOR signaling pathway is the most frequently activated signaling network in cancer and recurring mutations in this network have been identified, including mutations (PIK3CA, AKT, and PTEN), amplifications (PIK3CA, PIK3CB and AKT) and deletions (PTEN, INPP4B)." (PMID 26989080, 2016). "Dysregulated PI3K/AKT/mTOR signalling has been implicated in tumor progression and metastasis in multiple cancers of epithelial origin and recent data has begun to elucidate that these signalling pathways may be critical in STS." (PMID 26952093, 2016). "Although the magnitude of the effect of an individual mTOR SNP on cancer susceptibility appears to be weak, its interaction with functionally relevant variants and environmental factors might have a greater effect on oncogenesis." (PMID 27462867, 2016). "However, previous studies on the association of mTOR polymorphisms with predisposition to different cancer types are somewhat contradictory." (PMID 27462867, 2016). "Several components of the PI3K/PTEN/AKT/mTOR pathway are frequently mutated in human cancers." (PMID 27551323, 2016). "Not only does FAM83B activate MAPK and PI3K/AKT/mTOR signaling, but it may also participate in cancer-associated Wnt signaling." (PMID 27221039, 2016). "Furthermore, a number of studies have shown that mTOR genetic polymorphisms correlated with an individual's susceptibility to a variety of human cancers." (PMID 27533457, 2016).
cancer (continued). "The mTOR-mediated pathway is widely implicated in cancer and has been validated as an oncotarget." (PMID 27274989, 2016). "The present systematic review evaluated the overall effect of mTOR polymorphisms on cancer risk, and the updated meta-analysis evaluated the most commonly investigated mTOR polymorphisms: rs2536, rs2295080, rs1883965, rs1034528, rs17036508, rs3806317 and rs1064261." (PMID 27462867, 2016). "The study of mTOR polymorphisms has mainly focused on cancer susceptibility in recent years." (PMID 27462867, 2016). "Therefore, we performed a systematic review and updated meta-analysis of the available evidence regarding the relationship between mTOR single nucleotide polymorphisms (SNPs) and cancer risk." (PMID 27462867, 2016). "Thus, the dysregulation of mTOR pathway is implicated in an increasing number of diseases, including cancer, type 2 diabetes, and neurodegeneration (reviewed in7)." (PMID 27748082, 2016). "Two previous reports have examined the role of mTOR mutations in cancer." (PMID 26255626, 2015). "Recent cancer genome sequencing efforts have led to the identification of point mutations in mTOR." (PMID 26255626, 2015). "All these results support the proposition that GRP78 induced autophagy during IPC might be associated with AMPK - mTOR pathway, in agreement with the recent studies in cancer cells." (PMID 25885223, 2015). "Both the mTOR and Akt pathways have been implicated in various types of cancers." (PMID 26635517, 2015). "Recent studies suggest that the mammalian target of rapamycin (mTOR) kinase and downstream effectors may be implicated in the development of chronic inflammatory, neuropathic, and cancer pain." (PMID 25685786, 2015). "In addition to cancer, there is interest in the pathogenic role of mTOR in obesity, diabetes, and autism." (PMID 26180685, 2015). "However, while the use of mycophenolate was associated with a reduced cancer incidence, probably because its administration is correlated to calcineurin inhibitor dose reduction, mTOR inhibitors have shown a direct antineoplastic effect." (PMID 26185750, 2015). "Another function of mTOR that has been associated with cancer development is tumour angiogenesis." (PMID 25923415, 2015). "It has been observed that mTOR is often overexpressed and activated in a wide variety of human cancers but the underlying mechanisms remains unclear." (PMID 26078354, 2015). "Indeed, genetic knockout of mTOR is associated with decreased formation of spontaneous cancers in mice." (PMID 26056367, 2015). "Our meta-analysis of mTOR rs2295080 and cancer risk provided further evidence that mTOR SNPs might modulate cancer susceptibility." (PMID 25654238, 2015). "The PI3K/AKT/mTOR axis promotes survival and is a frequently mutated pathway in cancer." (PMID 26460954, 2015). "Mutations in PI3K/AKT/mTOR signaling can associate with disorders with a high incidence of cancers." (PMID 26421002, 2015). "This cohort contains known regulators of mTOR complex 1 and is significantly enriched in genes whose depletion affects the proliferation/viability of the large set of cancer cell lines in the Achilles database in a manner paralleling that caused by mTOR depletion." (PMID 25790369, 2015). "In addition, activation of the PI3K/mTOR pathway is associated with cancer and strategies aimed to neutralize their activation are in clinical development in different solid tumors." (PMID 26418718, 2015). "Furthermore, multivariate Cox regression analysis revealed that overexpression of PI3K/Akt/mTOR pathway proteins in STn+ MIBC was independently associated with approximately 6-fold risk of death by cancer (p = 0.039)." (PMID 26569621, 2015). "It should be clarified whether the more sustained inhibition of PI3K/Akt/mTOR signaling activity is also associated with more treatment-related toxicities in cancer patients." (PMID 24387108, 2014).
cancer (continued). "Recently, a number of case-control studies reported that the polymorphisms in mTOR gene were associated with individual's susceptibility to cancer risk and clinical outcome, but these studies were limited to modest sample size, different ethnicity, and statistical power." (PMID 24816861, 2014). "Given the crucial role of mTOR in multiple cellular functions, such as in cell death and survival, as well as angiogenesis, our findings of an association between the rs2295080 and cancer risk are biologically plausible." (PMID 24816861, 2014). "The activation of the MAPK and PI3K/AKT/mTOR pathways is implicated in the majority of cancers." (PMID 25401499, 2014). "In conclusion, this meta-analysis indicated the common polymorphisms in mTOR gene might be genetic risk factors for the carcinogenesis and clinical outcomes of cancer patients." (PMID 24816861, 2014). "Activated mTOR (pmTOR) has been shown to be associated with tumors in a number of cancer tissues." (PMID 25120661, 2014). "Thus, our findings on the influence of mTOR polymoprhisms on cancer risk only represent Chinese population." (PMID 24816861, 2014). "Moreover, genes in the differential network, particularly those involved in the pathways such as mTOR, insulin, and apoptotic signaling, showed association with cancer." (PMID 25057922, 2014). "mTOR signaling implicated in inflammatory, metabolic, degenerative, proliferative and cancer." (PMID 24797175, 2014). "Moreover, activation of the PI3K/Akt/mTOR pathway confers resistance to various cancer therapies and is often associated with a poor prognosis." (PMID 24969552, 2014). "Aberrant activation of mTOR signaling is closely implicated in a variety of cancers." (PMID 24626155, 2014). "Genetic polymorphisms in mTOR gene may be associated with cancer risk and clinical outcomes of cancer patients by affecting mTOR gene expression or its activation." (PMID 24816861, 2014). "Inactivating mutations in TSC1 are also common in cancer and based on the clinical evidence in a related genetic disease, mTOR inhibitors might also be considered as a treatment option." (PMID 25593991, 2014). "Therefore, we carried out a meta-analysis on all eligible studies to estimate the association between the genetic polymorphisms in mTOR gene and overall cancer risk as well as clinical outcomes." (PMID 24816861, 2014). "However, in human PDAC, mTOR phosphorylation was more closely associated with cancer cells than Akt phosphorylation, which was found in the neoplastic ducts, but also in acinar, islet and stroma cells." (PMID 24670043, 2014). "MTOR activation has also been associated with cancer development." (PMID 25533006, 2014). "In the 8p12/11q13 coamplified regions, EIF4EBP1 and RPS6KB2 could be co-targeted and play a synergistic role associated with the development and cancer progression as AKT/MTOR activators." (PMID 24416132, 2014). "Taken these results together, it is plausible that mTOR rs2295080 polymorphism could influence the expression level of mTOR and individual susceptibility to various cancers." (PMID 23555892, 2013). "Further, compelling evidence revealed that the dysregulation of mTOR is linked to the development of chronic diseases including insulin resistance, diabetes, cardiovascular disease, and obesity; as well as progression of various types of cancer." (PMID 23783557, 2013). "Likewise, Pik3cd, involved in the immune response and in cancer is implicated in the mTOR pathway with Ddit4 (also known as Redd1) and Tsc1/2." (PMID 23927422, 2013). "A number of studies have investigated the role of single nucleotide polymorphisms (SNPs) of mTOR gene in the etiology of cancers in various organs, including esophageal cancer, lung cancer, bladder cancer, colon cancer, rectal cancer, and acute lymphoblastic leukemia." (PMID 23555892, 2013).
cancer (continued). "The PI3K/Akt/mTor system also connects to transcriptional activation associated with cancer EMT." (PMID 23055980, 2012). "In addition, human cancer patients harboring PIK3CA mutations are sensitive to targeted therapy using the mTOR inhibitor everolimus, while human cancer patients carrying Kras mutations are resistant to the treatment." (PMID 22666248, 2012). "In addition, stronger induction of EEF2 phosphorylation mediated by AMPK activators and mTOR inhibitor was linked to more effective cancer cell growth inhibition." (PMID 23443080, 2012). "Mutations in the mTOR pathway of cancer cells may result in resistance to mTOR inhibition and prevent any action of the mTOR inhibitors." (PMID 22214493, 2012). "Recent studies show that mTOR signaling may be involved in mechanisms underlying the regulation of biological behaviors of cancer stem-like cells." (PMID 23443123, 2012). "Genetic variations in a PTEN/AKT/mTOR signaling axis may influence cellular functions including cell growth, proliferation and apoptosis, and then increase the individual’s risk of cancer." (PMID 22815832, 2012). "The PI3K/Akt/mTOR axis plays a decisive role in the negative regulation of autophagy, and the constitutive activation of this pathway has been implicated in many human cancers." (PMID 22496691, 2012). "Considering the role of mTOR in facilitating cancer development and progression, the reduced levels of mTOR owing to the rs2295080 variant in the promoter may decrease cancer susceptibility, which may explain our findings in the association studies." (PMID 23209702, 2012). "mTOR/S6K pathway is linked recently to hypoxia mechanism in cancers." (PMID 22570651, 2012). "(Furthermore, cancer cells have constitutively over-activated by mutations mTOR and MAPK pathways)." (PMID 21297220, 2011). "Thus far, the crucial factors recognized for producing the cancer metabolic phenotype appear to be the oncogenic mutations that alter growth factor signaling through the PI3K/Akt/mTOR pathway." (PMID 21573193, 2011). "Aberrant activation of the mTOR pathway has been implicated in the growth of various human cancers." (PMID 22145042, 2011). "Gerosuppressant metformin cannot distinguish between mTOR-driven program (which drives growth, fitness and the onset of reproduction early in life) and quasi-program (which causes menopauses, diseases such as cancer and aging later in life, when the mTOR-driven program becomes aimless)." (PMID 21483040, 2011). "Finally, therapies that indirectly inhibit mTOR have also shown clinical promises in cancer therapy and further underline the importance of mTOR in cancer biology." (PMID 24212820, 2011). "In this respect, the Ras/Raf/MEK/ERK and Ras/PI3K/PTEN/mTOR/Akt pathways represent key therapeutic targets as they are often dysregulated by various mutations in cancer and these cascades control the activities of many proteins critical for cell growth and metastasis." (PMID 21422497, 2011). "Whereas the cancer risk of this approach should be carefully examined, we have recently observed that epithelial stem cells are endowed with protective mechanisms triggering stem cell differentiation or senescence upon aberrant activation of mTOR." (PMID 20498714, 2010). "mTOR signaling pathway and its downstream serine/threonine kinase p70S6k were frequently activated in human cancers and the dysregulation of the mTOR pathway is implicated as a contributing factor to various human disease processes, especially various types of cancer." (PMID 20003385, 2009). "Since inhibiting mTOR activity leads to cancer cell death while high levels of telomerase activity is associated with cancer cell proliferation, it is possible that mTOR may directly or indirectly regulate telomerase activity." (PMID 17996122, 2007). "In summary, through these actions AMPK might reduce the risk for developing cancers for which molecules such as mTOR may act like mitogens." (PMID 16570048, 2006).
cancer (continued). "Additionally, genetic polymorphisms in the mTOR pathway are linked to cancer risk and hormone receptor status in AA women, suggesting that variations in these genes may affect disease susceptibility and metabolic flexibility." (PMID 40563920, 2025). "Thus, we hypothesised that cancers harbouring dual KRAS mutation/STK11 inactivation might be particularly vulnerable to targetting mTOR signalling." (PMID 40069402, 2025). "The dynamic interplay between mTOR and mitochondrial networks governs key aspects of bioenergetics, redox balance, and cell fate decisions and is increasingly implicated in pathophysiological contexts ranging from cancer and aging to neurodegenerative and immune disorders." (PMID 41469379, 2025). "In addition to mTOR, there are other pathways associated with protein synthesis in various cancers." (PMID 39779613, 2025). "Clinical studies suggest that mTOR inhibitors reduce the risk of cancer following organ transplant, which may be linked to inhibition of the mTOR pathway (Akt/PI3K) and blocking of mRNA translation of some procarcinogenic factors, such as VEGF, cyclin D1, and IL-10." (PMID 40867689, 2025). "Among these pathways, the phosphoinositide 3-kinase (PI3K)/Akt/mammalian target of rapamycin (mTOR) pathway is particularly critical, as its dysregulation is frequently linked to tumor progression, resistance to therapy, and poor outcomes across multiple cancer types." (PMID 41586220, 2025). "However, recent publications have found that pharmacological suppression of mTOR activity in cancer cells can cause chemoresistant cell populations to persist through regulation of autophagy and G2/M cell cycle arrest; mTOR activation can increase chemosensitivity and predict better survival." (PMID 40745386, 2025). "Translational control, whether it be mTOR or ISR regulation has been implicated in pro-survival mechanisms in a variety of diseases including cancer where targeting mTOR and PERK have been proposed as new generation therapeutic strategies in different contexts." (PMID 38323074, 2024). "Extensive studies have established a dominant role for mTOR in regulating cellular growth and metabolism in response to growth factors and nutrients and reveal that the mTOR signaling pathway is implicated in the progression of cancer as well as the ageing process." (PMID 38541642, 2024). "However, disruptions in mTOR have been linked to numerous diseases, including cancer, metabolic diseases, and neurological diseases, suggesting that abnormal mTOR signaling in the brain can affect numerous pathways related to mitochondrial function and energy metabolism." (PMID 37450931, 2024). "While overactive mTOR signaling is associated with many cancer types, moderate mTOR activity may help maintain normal cell functions and prevent excessive proliferation of cancer cells." (PMID 39634548, 2024). "Additionally, coffee consumption, both regular and decaffeinated, has been linked to modulation of aging-related pathways like mTOR, which could mitigate risks of age-related diseases such as cancer." (PMID 39723163, 2024). "However, the combined use of STAT3 inhibitors with PI3K/AKT/mTOR inhibitors can synergistically induce apoptosis in PTEN-deficient cancer cell lines, highlighting the potential of this combined therapeutic strategy in the treatment of PTEN-deficient tumors, including gastric cancer." (PMID 39309860, 2024). "Thus, we investigated whether a combined inhibition of NUAK1 and mTOR may be an approach to avoid Akt reactivation, causing cancer cell death." (PMID 38135881, 2023). "One of the most important signaling pathways in response to insulin signals, PI3K/Akt/mTOR, plays a crucial role in regulating malignant phenotypes such as cell proliferation, differentiation, invasion, and migration and is closely associated with the occurrence and development of malignant tumors." (PMID 38053170, 2023).